GPR158 (G protein-coupled receptor 158)
Diseases named in the same sentence as GPR158 in open-access papers (continued):
Sharing a sentence is not in itself a finding about the gene and the disease.
osteosarcoma (4 papers, 2022 to 2024). A usually aggressive malignant bone-forming mesenchymal neoplasm, predominantly affecting adolescents and young adults. "And then arrested osteosarcoma cell proliferation and angiogenesis by inducing miR-613-mediated GPR158 inhibition." (PMID 37377390, 2023). "In osteosarcoma, miR613 inhibits the expression of GPR158, leading to the inhibition of the proliferation and angiogenesis of osteosarcoma." (PMID 36467406, 2022). "The summarized findings supported the inhibiting effect of Bev on the angiogenesis of osteosarcoma cells by regulating the EV-MIAT/miR-613/GPR158 axis." (PMID 35347106, 2022). "In conclusion, the Bev-mediated MIAT/miR-613/GPR158 regulatory feedback revealed a new molecular mechanism in the pathogenesis of osteosarcoma angiogenesis." (PMID 35347106, 2022). "Among the 15 candidate mRNAs, GPR158 was detected to be abundantly expressed in osteosarcoma samples." (PMID 35347106, 2022). "Finally, we sought to identify the role of Bev in osteosarcoma angiogenesis by regulating the EV-MIAT/miR-613/GPR158 axis." (PMID 35347106, 2022). "We provide the first evidence for the promoting activity of GPR158 in osteosarcoma cell proliferation and angiogenesis, suggesting that GPR158 might be a potential therapeutic strategy for GPR158." (PMID 35347106, 2022). "We, therefore, aimed to investigate its role in osteosarcoma in this study and the interaction with the MIAT carried by osteosarcoma patient serum-derived EVs (EV-MIAT)/miR-613/GPR158 axis to participate in the potential molecular mechanism of Bev in angiogenesis during osteosarcoma." (PMID 35347106, 2022). "Besides, a decline of GPR158 expression was seen in osteosarcoma cells transfected with miR-613 mimic, whereas a contrary trend was evident upon miR-613 inhibitor treatment." (PMID 35347106, 2022). "Besides, serum-EVs could transfer MIAT (EV-MIAT) into osteosarcoma cells, where it is competitively bound to miR-613 to elevate GPR158, thus promoting osteosarcoma cell proliferation and angiogenesis." (PMID 35347106, 2022). "Overall, our study unveils that Bev can attenuate osteosarcoma cell proliferation and angiogenesis by inhibiting EV-MIAT and facilitating miR-613-mediated GPR158 inhibition." (PMID 35347106, 2022). "These lines of evidence demonstrate that Bev regulates miR-613-mediated GPR158 by inhibiting EV-MIAT, thus suppressing osteosarcoma cell proliferation and angiogenesis." (PMID 35347106, 2022). "Interestingly, serum samples from osteosarcoma patients could transfer via EVs the myocardial infarction-associated transcript (MIAT), promoting the proliferation of osteosarcoma cell lines and angiogenesis in HUVECs by sponging miR-613 and upregulating G protein-coupled receptor 158 (GPR158)." (PMID 38392967, 2024). "Furthermore, Bev arrested osteosarcoma cell proliferation and angiogenesis by inhibiting EV-MIAT and inducing miR-613-mediated GPR158 inhibition." (PMID 35347106, 2022).
ovarian carcinoma (4 papers, 2019 to 2022). A malignant neoplasm originating from the surface ovarian epithelium. "GPR158 was also shown to be a histotype-specific prognostic biomarker in mucinous (MC) ovarian carcinomas, with elevated GPR158 expression patterns indicating unfavorable overall survival." (PMID 35456013, 2022). "Further, a previously reported study also suggested GPR158 as an important oncogenic factor to promote ovarian carcinoma cell proliferation and progression." (PMID 35347106, 2022). "For instance, given the expression level of GPR158 in ovarian cancer, GPR158 might have a similar effect through estrogen as that of androgen in PCa." (PMID 36467406, 2022). "In estrogen-sensitive breast cancer, the expression of GPR158 is down-regulated following the withdrawal of estrogen or the use of estrogen antagonists, suggesting that GPR158 may be a novel biomarker for the prognosis of ovarian carcinoma and breast cancer." (PMID 36467406, 2022). "KM plotter was used to validate the prognostic value of COL3A1, GPR158 and PITHD1 in an external ovarian cancer dataset." (PMID 31533654, 2019). "Survival analysis revealed that the RNA expression levels for the COL3A1, GPR158 and PITHD1 genes were significantly correlated with that shown on the protein expression levels, proposing them as prognostic factors for ovarian carcinoma (COL3A1) and in MC (GPR158) and CCC histotypes (PITHD1)." (PMID 31533654, 2019). "Surprisingly, none of the MC ovarian carcinoma patients classified in the GPR158-negative expression group died of ovarian carcinoma." (PMID 31533654, 2019).
Cognitive impairment (3 papers, 2022 to 2025). Abnormal cognition is characterized by deficits in thinking, reasoning, or remembering. "Additionally, the post-translational modification profile of GPR158 holds promise as a potential factor associated with diseases, particularly concerning diabetes-related cognitive impairment." (PMID 40337551, 2025). "OCN binds to GPR158, activating the IP3R and retinoblastoma-associated protein 48 (RbAp48) pathways to upregulate BDNF expression, enhance BDNF-enriched vesicle transport, and increase action potential frequency and LTP in the MF pathway, thereby improving cognitive deficits in aged mice." (PMID 40337551, 2025).
esophageal squamous cell carcinoma (3 papers, 2022 to 2025). Esophageal squamous cell carcinoma (ESCC) is a type of esophageal carcinoma (EC) that can affect any part of the esophagus, but is usually located in the upper or middle third. "GPR158 is also hypermethylated in many esophageal squamous cell carcinoma (ESCC) samples and can be used as a risk factor marker." (PMID 35456013, 2022). "Moreover, alterations in GPR158 methylation have been observed in esophageal squamous cell carcinoma and melanoma, indicating that GPR158 may serve as a potential risk marker beyond NDs." (PMID 40337551, 2025).
ocular hypertension (3 papers, 2013 to 2022). Abnormally high intraocular pressure. "The GPCR Family C orphan GPR158 came to our attention through a small pharmacogenomic study we conducted on risk for glucocorticoid (GC)-induced ocular hypertension (OH)." (PMID 23451275, 2013). "Since GCs stimulate GPR158 expression, the result is consistent with a role for elevation of GPR158 expression in GC-induced ocular hypertension." (PMID 23451275, 2013). "Taken together, GPR158 may develop into a uniquely effective drug target for ocular hypertension and glaucoma in the future." (PMID 35456013, 2022). "GPR158 reduces TBM cell monolayer permeability by increasing the expression of tight junction-specific proteins, resulting in the obstruction of aqueous humor backflow and the occurrence of ocular hypertension, which may eventually lead to primary open-angle glaucoma." (PMID 36467406, 2022).
astrocytomas (2 papers, 2018 to 2022). "GPR158 expression was highest in the CNS (n = 5) and in oligodendrogliomas, followed by astrocytomas (p < 0.0001), and significantly lower in eGBM and GBM (p < 0.0001)." (PMID 29720725, 2018). "Again, GPR158 expression strongly correlated with histological entities being highest in CNS cortex, followed by oligodendrogliomas, whilst astrocytomas stained much weaker, but had still a clearly visible fine granular cytoplasmic stain." (PMID 29720725, 2018). "To correlate GPR158 expression with clinically, diagnostically and biologically relevant tumour entities, we defined oligodendrogliomas (O, n = 83) as IDH mutant, 1p/19q co-deleted tumours, and astrocytomas (A, n = 138) as IDH mutant, ATRX mutant tumours with no 1p/19q codeletion." (PMID 29720725, 2018).
brain tumor (2 papers, 2018 to 2025). "On the one hand, the overexpression of GPR158 in brain tumor stem-like cells (BTSCs) has inhibited cell proliferation and migration while promoting cell differentiation and apoptosis." (PMID 40337551, 2025). "However, the role of GPR158 in brain tumor cells appears to be multifaced." (PMID 40337551, 2025).
breast carcinoma (2 papers, 2015 to 2022). "Perhaps of relevance, data mining results obtained in the current study indicate that RGS7 is co-expressed with GPR158 in breast cancer along with many NE markers." (PMID 25693195, 2015). "Another gene expression microarray study showed down-regulation of GPR158 by withdrawal of estrogen in human estrogen-sensitive breast cancer cells, or by tamoxifen (anti-estrogen) treatment." (PMID 25693195, 2015).
epilepsy (2 papers, 2019 to 2021). A brain disorder characterized by episodes of abnormally increased neuronal discharge resulting in transient episodes of sensory or motor neurological dysfunction, or psychic dysfunction. "The increased excitability observed in Gpr158 KO could possibly compensate for the reduced SC drive, as previously reported in an epilepsy model." (PMID 31749686, 2019). "Herein, we identified seven genes (NCL, SEPHS2, PA2G4, SLC35G2, MYO1C, GPR158, and POU3F1) with de novo variants but unknown pathogenicity that were not previously associated with epilepsy." (PMID 34489640, 2021).
migraine (2 papers, 2019 to 2022). "In particular, HCN3 belong to hyperpolarization-activated potassium channels family proteins involved in trigeminal ganglion neuron activation, while NAV3 and GPR158 are emerging in migraine." (PMID 31252698, 2019). "The in-silico analysis showed that the target genes, i.e., HCN3, NAV3, GPR158 for miR-34a-5p and MTPN for miR-375, are involved in trigeminal pain circuit of migraine." (PMID 35682695, 2022).
Obesity (2 papers, 2022 to 2025). Accumulation of substantial excess body fat. "We also for the first demonstrated that OCN/GPR158 signaling is vital for cognitive integrity in metabolic dysfunctions and that obesity induces resistance to OCN’s cognition-promoting effects via MT1-MMP-mediated cleavage of GPR158." (PMID 40983624, 2025). "We report the identification of a direct negative regulator of GPR158, establishing MT1-MMP as a potential therapeutic target for preserving cognitive integrity in aging and obesity." (PMID 40983624, 2025). "We are the first to report MT1-MMP as a regulator of GPR158, revealing that MT1-MMP-mediated proteolytic cleavage of GPR158 is crucial for OCN-dependent cognitive functions in aging and obesity." (PMID 40983624, 2025). "Our insights into OCN/GPR158 signaling regulation suggest a physiological mechanism for endogenous OCN sensitivity in the central nervous system in aging and obesity." (PMID 40983624, 2025). "Mechanistically, MT1-MMP proteolytically inactivates G-protein-coupled receptor 158 (GPR158), a hippocampal receptor for osteocalcin (OCN) that is important for the maintenance of cognitive integrity, thus suppressing the ability of the OCN-GPR158 axis to promote cognition in aging and obesity." (PMID 40983624, 2025).
Parkinson disease (2 papers, 2024 to 2025). A progressive degenerative disorder of the central nervous system characterized by loss of dopamine producing neurons in the substantia nigra and the presence of Lewy bodies in the substantia nigra and locus coeruleus. "Moreover, this study did not use a GPR158 knockout Parkinson's disease model to determine whether osteocalcin truly exerts its neuroprotective effect through this central receptor in Parkinson's disease rats." (PMID 39252492, 2024).
primary open angle glaucoma (2 papers, 2013 to 2022). "Since GCs stimulate GPR158 expression, the results are consistent with a role for elevation of GPR158 expression in GC-induced OH, which can lead to primary open angle glaucoma (POAG)." (PMID 23451275, 2013). "Owing to the pressure regulation of GPR158 in TBM cells, it could be reckoned that inhibition of GPR158 expression may be a new strategy for the treatment of glaucoma." (PMID 36467406, 2022).
age (1 paper, 2023). A temporal measurement of the time period elapsed since an identifiable point in the life cycle of an organism. "Further studies identified that G-protein-coupled receptor 158 (Gpr158) is the receptor in CNS that OCN binds and combats age-related hippocampal-dependent cognitive impairments." (PMID 36746932, 2023).
atherosclerosis (1 paper, 2024). A disease characterized by the build-up of fatty material and calcium deposition in the arterial wall resulting in partial or complete occlusion of the arterial lumen. "GPR158 is highly expressed in the brain and associates to nervous system-related tumors and cardiac fibrosis, whereas C5AR1 associates to atherosclerosis, coronary artery disease (CAD), and CD." (PMID 39187864, 2024).
cognitive decline (1 paper, 2025). "Aging results in a decrease in OCN bioavailability and an MT1-MMP-mediated reduction in GPR158 expression, both of which contribute to impaired OCN/GPR158 signaling and consequently, age-related cognitive decline." (PMID 40983624, 2025).
Hyperglycemia (1 paper, 2025). An increased concentration of glucose in the blood. "Conversely, chronic hyperglycemia can induce upregulation of the DNA-modifying enzymes (Dnmt1/3b) in the rat hippocampus, which inhibits the expression of GPR158 through epigenetic mechanisms such as methylation." (PMID 40337551, 2025). "As discussed in Section 2.3, chronic hyperglycemia results in increased methylation of GPR158 in the rat hippocampus, adversely affecting learning and memory." (PMID 40337551, 2025).
lung carcinoma (1 paper, 2018). "A role of GPR158 long non-coding antisense (AS) RNA in lung cancer has recently been described, where high expression of GPR158 AS1 correlates with poorer overall survival." (PMID 29720725, 2018).
metastatic tumor (1 paper, 2015). "Searching for other possible roles for GPR158, we identified a published microarray study showing GPR158 as one of the genes upregulated in androgen ablation-resistant metastatic tumor as compared to primary prostate tumors." (PMID 25693195, 2015).
neurocytomas (1 paper, 2025). "Although these studies indicate that GPR158 may exhibit contrasting roles in different types of neurocytomas, either promoting or inhibiting tumor progression, this does not diminish the potential of the OCN/GPR158 axis as a crucial biomarker for diagnosing neurological diseases." (PMID 40337551, 2025).
prostate tumors (1 paper, 2015). "Consistent with this, we found that GPR158 protein expression is highly increased in prostate tumor tissue from all three lobes of prostate isolated from a Pten−/− mice, compared with the normal prostate from Pten+/+ mice." (PMID 25693195, 2015). "GPR158 expression was increased at the invading front of prostate tumors that formed in the genetically defined conditional Pten knockout mouse model, and co-localized with elevated AR expression in the cell nucleus." (PMID 25693195, 2015).
prostatic adenocarcinoma (1 paper, 2015). "A selection of normal prostate and prostatic adenocarcinoma samples included in the database reveal a similar range of distributions, but there is not enough information to determine whether a specific subcellular location of GPR158 might associate with tumorigenesis or progression to CRPC." (PMID 25693195, 2015). "To determine whether GPR158 might be upregulated in human PCa, we searched the cBioPortal, Cancer Genomics database of the Memorial Sloan Kettering Cancer Center, and identified a dataset called “Prostate Adenocarcinoma (MSKCC, Cancer Cell 2010) Study”." (PMID 25693195, 2015).
spinal muscular atrophy (1 paper, 2025). A motor neuron disease that affect the muscles, and characterized by muscle weakness and atrophy resulting from progressive degeneration and irreversible loss of the anterior horn cells in the spinal cord (i.e., lower motor neurons) and the brain stem nuclei. "Reduced expression of osteoblast markers, including OCN and osteopontin, has been observed in spinal muscular atrophy (SMA), while GPR158 knockout impairs novelty preference in autism spectrum disorders (ASD)." (PMID 40337551, 2025).
toxoplasmosis (1 paper, 2024). A parasitic disease contracted by the ingestion or fetal transmission of toxoplasma gondii. "The pivotal genes AAMDC, GPR158, RAD9A, STOML1and STRA13 identified in this study have the potential to serve as molecular therapeutic or immunotherapeutic targets for toxoplasmosis; however, their specific function mechanisms require further verification." (PMID 39935538, 2024).
type 2 diabetes (1 paper, 2022). "The lead variants in these loci indicated no significant heterogeneity between type 1 and type 2 diabetes apart from the GPR158 locus (pHET=0.005)." (PMID 35763030, 2022).